COL4A4 (collagen type IV alpha 4 chain)
Diseases named in the same sentence as COL4A4 in open-access papers (continued):
Sharing a sentence is not in itself a finding about the gene and the disease.
keratoconus (4 papers, 2009 to 2020). A degenerative, structural disorder of the eye, characterized by a cone-shaped protrusion of the cornea. "Allele frequencies and their significances in COL4A3 and COL4A4 polymorphisms between keratoconus patients and control population." (PMID 20029656, 2009). "Moreover, 2 SNPs in the COL4A4 gene identified by candidate gene studies were strongly associated with keratoconus in Whites, namely rs2229813 (P = 1.3 × 10−12, odds ratio (OR) = 2.38; I2 = 0) and rs2228557 (P = 4.5 × 10−7, OR = 0.54; I2 = 0)." (PMID 28676647, 2017). "In the COL4A4 gene, another SNP rs2228557, which was proposed in candidate gene studies, showed a significant summary P value (P = 4.5 × 10−7) in Whites, suggesting COL4A4 could be a genuine susceptibility gene for keratoconus in Whites." (PMID 28676647, 2017). "Therefore, it would be intriguing to check the COL4A4 SNPs in the GWAS data and assess their association with keratoconus." (PMID 28676647, 2017). "Genotype and allelic frequencies of COL4A4 rs2228557 and TIMP-1 rs4898 polymorphisms between keratoconus (KC) patients and healthy controls." (PMID 32864060, 2020). "We identified 8 SNPs in 6 genes/loci that were associated with keratoconus, i.e., FOXO1 rs2721051, FNDC3B rs4894535 and BANP-ZNF469 rs9938149 for the overall combined cohorts, and RXRA-COL5A1 rs1536482, IMMP2L rs757219 and rs214884, and COL4A4 rs2229813 and rs2228557 for Whites." (PMID 28676647, 2017). "Therefore, whether COL4A4 is a biomarker with differential effects on keratoconus among different ethnic groups has yet to be confirmed." (PMID 28676647, 2017). "Correlation of clinical and keratometric parameters with COL4A4 (rs2228557) and TIMP-1(rs4898) in keratoconus patients." (PMID 32864060, 2020). "In conclusion, we have prioritized 8 SNPs in 6 genes/loci as significant genetic markers for keratoconus in Whites, including FOXO1 rs2721051, RXRA-COL5A1 rs1536482, FNDC3B rs4894535, IMMP2L rs757219 and rs214884, and BANP-ZNF469 rs9938149, and COL4A4 rs2229813 and rs2228557." (PMID 28676647, 2017). "Alterations in collagen type IV, alpha-3 (COL4A3) and collagen type IV, alpha-4 (COL4A4) genes may be responsible for a decrease in collagen types I and III, a feature often detected in keratoconus (KC)." (PMID 20029656, 2009).
prostate carcinoma (4 papers, 2017 to 2024). A carcinoma that arises from epithelial cells of the prostate gland. "The diminished expression of COL4A4 is associated with poorer prognosis, while the downregulation of COL4A6 promotes prostate cancer progression and invasion." (PMID 38907304, 2024). "There were also 5 KLF5K369Q-downregulated and NTZ-upregulated genes whose lower expression levels in human prostate cancers were also significantly associated with worse overall survival, including TMPRSS2, CALB1, SPOCK2, COL4A4, and COL4A3." (PMID 36810084, 2023).
Renal cyst (4 papers, 2019 to 2026). A fluid filled sac in the kidney. "However, several lines of evidence support the possible involvement of the COL4A4 VUS variant in the cystic kidney phenotype." (PMID 41450889, 2025).
glomerulonephritis (3 papers, 2014 to 2025). A renal disorder characterized by damage in the glomeruli. "COL4A4 is associated with both autosomal dominant and recessive Alport syndrome (ADAS and ARAS), a condition characterized by glomerulonephritis, ESKD, and hearing loss." (PMID 40770708, 2025). "Further diseases linked to PPROM were nephritis or glomerulonephritis (ACE, COL4A3, COL4A4, IGF1, NOS2, REN, TNF)." (PMID 25264875, 2014).
autosomal dominant tubulointerstitial kidney disease (2 papers, 2024 to 2026). "The hypomorphic COL4A4 variant p.(Gly545Ala) predisposes to a mild clinical course and a tubulointerstitial phenotype, resembling autosomal dominant tubulointerstitial kidney disease or hypertensive nephropathy." (PMID 41531438, 2026).
Cirrhosis (2 papers, 2015 to 2025). A chronic disorder of the liver in which liver tissue becomes scarred and is partially replaced by regenerative nodules and fibrotic tissue resulting in loss of liver function. "Differential expression of COL4A4 and PACSIN3 was found in patients with NAFLD and cirrhosis compared to healthy individuals, and GSN, that is associated to HCC, was the most upregulated gene in cirrhosis." (PMID 40489530, 2025). "Although three other genes (COL4A4, COL6A2, COL5A3) were down-regulated in these patients, our results overall support the notion that white blood cells from patients with cirrhosis are predominately prone to produce collagen." (PMID 26317806, 2015). "The upregulated genes between cirrhosis and healthy included GSN, COL4A4, CHI3L1, and GLIS2." (PMID 40489530, 2025).
COVID-19 (2 papers, 2021 to 2023). A disease caused by infection with severe acute respiratory syndrome coronavirus 2. "All represented terms showed 5 common genes between our ORF-A549 cells and COVID-19 lung biopsies (COL1A1, COL4A3, COL4A4, COL5A1 and COL11A1)." (PMID 37545510, 2023).
esophageal tumor (2 papers, 2019 to 2021). "Additionally, COL4A4 was found to be downregulated in esophageal tumor tissues." (PMID 34960256, 2021). "Also, COL4A4 was also found to be down-regulated in esophageal tumor tissues." (PMID 31598423, 2019).
Familial Nephropathy (2 papers, 2011 to 2025). "Familial Nephropathy (FN) is a juvenile-onset fatal kidney disease, which has been well documented in the English cocker spaniel breed and is caused by a conserved mutation in the canine COL4A4, gene." (PMID 21346820, 2011). "Among the 7 patients with a VUS+ in COL4A5 and COL4A4, 6 reported a first-degree familial nephropathy, 6 had reached end-stage kidney disease." (PMID 40630292, 2025).
lung adenocarcinoma (2 papers, 2014 to 2025). A carcinoma that arises from the lung and is characterized by the presence of malignant glandular epithelial cells. "COL4A4 is downregulated in lung adenocarcinoma and is associated with various tumor microenvironment (TME) parameters, immune therapy response, and drug resistance." (PMID 39968416, 2025). "Although COL4A4, NFASC and ZNF137 show significant prognosis for overall survival and stage I, II in lung adenocarcinoma they failed to predict prognosis while correlating with the smoking history." (PMID 25401222, 2014).
nephritis (2 papers, 2011 to 2014). Inflammation of renal tissue. "WO:COL4A4 rdf:type WO:Gene;WO:isAssociatedWith WO:Nephritis." (PMID 21699718, 2011).
Obesity (2 papers, 2015 to 2025). Accumulation of substantial excess body fat. "Furthermore, obesity led to the up-regulation of sodium transporters (Slc13a1, Slc22a8, Slc17a1, Slc17a3) and the down-regulation of structural proteins (Col4a3, Col4a4) as well as Na/K-ATPase subunits encoded by Atp1a1, Atp1b1, suggesting impaired sodium metabolism and underlying renal injury." (PMID 41133844, 2025). "Consistent with findings from the early-stages of diet-induced obesity studies, our network analysis identified increased expression of common collagen-related ECM transcripts COL1A1, COL3A1, COL16A1, COL4A4, and COL6A3." (PMID 26678390, 2015).
cardiomyopathy (1 paper, 2022). A disease of the heart muscle or myocardium proper. "Genes in MCODE 2 (such as TPM4) were significantly involved in cardiomyopathy, and genes in MCODE 4 (such as COL4A3 and COL4A4) were involved in focal adhesion, ECM-receptor interaction, and PI3K-Akt signaling pathway." (PMID 35645614, 2022).
cyst (1 paper, 2025). A sac-like closed membranous structure that may be empty or contain fluid or amorphous material. "The COL4A4 variant may affect the stability and strength of the tubular cell–matrix interaction, rendering the tubular cells more susceptible to cyst formation." (PMID 41450889, 2025).
endometrial cancer (1 paper, 2023). Primary or metastatic malignant neoplasm involving the endometrium (mucous membrane that lines the endometrial cavity). "Overexpression of collagen-associated genes (COL4A4, COL19A1, COL6A6) occurs in the late stages of endometrial cancer, which could indicate that they partake in the progression of EC." (PMID 36982551, 2023).
fibrosis (1 paper, 2025). the formation of excess fibrous connective tissue in an organ or tissue in a reparative or reactive process. "Compared to the low-fibrosis group, expression of COL1A1 (P = 0.042) and COL1A2 (P = 0.032) was significantly higher in the high-fibrosis group, whereas COL4A4 expression (P = 0.041) was lower." (PMID 41049608, 2025).
glioblastoma (1 paper, 2025). The most malignant astrocytic tumor (WHO grade IV). "By comparing the expression level in different histological types of gliomas, COL4A1 and COL4A2 were better predictors of glioblastoma (AUC = 0.918 and 0.9), followed by COL4A3 and COL4A4 (AUC = 0.67 and 0.746)." (PMID 40351420, 2025).
glioma (1 paper, 2025). A benign or malignant brain and spinal cord tumor that arises from glial cells (astrocytes, oligodendrocytes, ependymal cells). "We found the high expressions in COL4A1 and COL4A2 were positively related to a worse prognosis of glioma patient, while, in COL4A3 and COL4A4 were predicted to a better prognosis." (PMID 40351420, 2025).
Goodpasture's syndrome (1 paper, 2007). "Defects in Type IV collagen genes have been shown to influence Goodpasture's syndrome, an autoimmune disease affecting the lung, and both COL4A4 and COL4A3 lie in this region, sharing a common promoter." (PMID 17903307, 2007).
liver fibrosis (1 paper, 2025). "Intriguingly, we found that LAPNTG mice are protected from liver fibrosis as reflected by a greatly reduced expression of fibrotic genes such as Col1a1, Col3a1, Col4a4, TGF-β, and SMA." (PMID 39792554, 2025). "Doing so, we found that the deletion of adiponectin in HSCs accelerates the development of liver fibrosis as reflected by significant increases in SMA, Col1a1, Col3a1, Col4a4, and leptin, but not TGF-β expression in the liver." (PMID 39792554, 2025).
liver steatosis (1 paper, 2024). "However, the other liver steatosis gene markers, such as Thbs2, Lum, Lamc3, Lama2, Akr1b10, Col4a4, A2m, and C7, were not significantly different between the db-HF and db-HC groups." (PMID 38613031, 2024).
microtia (1 paper, 2017). "Thus we suggest that the two genes, COL4A4 and COL11A1, may be strongly involved in the mechanism of microtia and are worth exploring in the context of the pathogenesis of microtia." (PMID 28968992, 2017).
Multiple renal cysts (1 paper, 2023). The presence of many cysts in the kidney. "Moreover, some reports have shown that COL4A3 and COL4A4 mutations have been detected in patients with multiple renal cysts." (PMID 36981034, 2023).
nephromegaly (1 paper, 2024). "Cystic nephromegaly mimicking ADPKD has been reported in patients with COL4A3/COL4A4 variants but in the present series only 3.8% of patients had nephromegaly." (PMID 38317457, 2024).
preeclampsia (1 paper, 2024). Preeclampsia is a hypertensive disorder of pregnancy that is characterized by new-onset hypertension with proteinuria presenting after 20 weeks of gestation, and depending on mild or severe forms may initially present with severe headache, visual disturbances, and hyperreflexia. "A woman with both COL4A3 and COL4A4 pathogenic variants (Patient No. 1446) was diagnosed with preeclampsia while pregnant with her first child at 24 years old and CGN at 29 years old; RRT was initiated at 31 years old." (PMID 38765603, 2024).
refractive error (1 paper, 2022). A defect in the focusing of light on the retina as in astigmatism, myopia, or hyperopia. "Our WES GWAS analysis and fine-mapping study implicated two novel genes as conferring susceptibility to refractive error (COL4A4 and ATM)." (PMID 35022715, 2022).
renal dysfunction (1 paper, 2025). "Pathogenic variants in the COL4A3, COL4A4, or COL4A5 genes disrupt the proper assembly and structure of collagen type IV, leading to impaired GBM integrity and progressive renal dysfunction, and may also affect ocular and cochlear structures." (PMID 40852417, 2025).
sarcoidosis (1 paper, 2025). Sarcoidosis is a multisystemic disorder of unknown cause characterized by the formation of immune granulomas in involved organs. "However, unlike NL and NXG, COL4A4, COL6A6, and COL11A1 were not significantly upregulated in sarcoidosis fibroblasts, and CCL5 was only modestly upregulated." (PMID 39989459, 2025).
systemic sclerosis (1 paper, 2025). A chronic disorder, possibly autoimmune, marked by excessive production of collagen which results in hardening and thickening of body tissues. "Also, the upregulation of COL4A4, COL8A1, and COL11A1 in systemic sclerosis fibroblasts was not nearly as strong as that observed in NL fibroblasts." (PMID 39989459, 2025).
kidney disease (45 papers, 2011 to 2026). "More data on disease risk attributable to heterozygous P/LP autosomal variants in COL4A3/COL4A4 is needed before these are reported to patients undergoing genomic testing for reasons unrelated to evidence of kidney disease." (PMID 39673454, 2025). "In view of this very low percentage of patients with P/LP variants in the COL4A3/COL4A4 genes with cystic nephromegaly, it seems advisable to exclude other inherited kidney diseases when cystic nephromegaly is present." (PMID 38317457, 2024). "In this study of 42 individuals with a variant in one of the alleles of the COL4A3/COL4A4 gene from 17 Dutch families, we investigated kidney disease symptoms and kidney biopsies." (PMID 36925663, 2023). "According to the inclusion and exclusion criteria, our attention was caught by five COL4A3/COL4A4 variants detected in five patients from 343 patients with hereditary kidney diseases." (PMID 35386907, 2022). "Five unclassified COL4A3/COL4A4 variants, which were detected in five of 343 patients with hereditary kidney diseases, were analysed." (PMID 35386907, 2022). "WES identified 2 novel and 2 known pathogenic COL4A3/COL4A4/COL4A5 mutations in 3 families with previously unexplained inherited kidney disease." (PMID 25381091, 2014). "Yet it is important to acknowledge that the risk associated with heterozygosity for a COL4A3/COL4A4 variant in a family known to be affected by severe kidney disease is likely higher than in unselected populations, given the shared genetic and environmental background." (PMID 39673454, 2025). "In addition, the glomerular basement membrane was found to be thinner in patients with a variant in COL4A3/COL4A4 than in patients with other kidney disorders." (PMID 36925663, 2023). "Here, we describe in-depth clinical, pathological, and genetic investigations of 42 patients from 17 families with 8 different mono-allelic variants in COL4A3 or COL4A4, identified with a kidney disorders gene panel using whole exome sequencing in a diagnostic approach." (PMID 36925663, 2023). "Moreover, some studies suggested that COL4A4 heterozygous mutation-associated type IV collagen kidney disease resulted in heterogeneous phenotypes." (PMID 34964757, 2021). "COL4A4 c.G2636A, a novel variant, co-segregated with renal disease among maternal relatives." (PMID 25381091, 2014). "The presence of COL4As (COL4A3, COL4A4, COL4A5) gene variants and other genetic variants associated with kidney disease was examined using a comprehensive gene panel." (PMID 40753325, 2025). "Alport kidney disease (AKD) is a spectrum of kidney disorders caused by pathogenic variants in the α3, α4, and α5 chains of collagen type IV, which are translated from the COL4A3, COL4A4, and COL4A5 genes, respectively." (PMID 39907758, 2025). "Variations in the genes that encode these α chains—especially COL4A1, COL4A3, COL4A4, and COL4A5—have been associated with several kidney disorders, which involve not only glomerular dysfunction but also the formation of cysts." (PMID 40565535, 2025). "We identified rare pathogenic variants in known monogenic kidney disease genes, including PKD1 and COL4A4, confirming their role in disease susceptibility." (PMID 40770708, 2025). "Mono-allelic variants in COL4A3 were identified in 5 index patients and in COL4A4 in 12 index patients.26, 27, 28, 29, 30, 31 All index patients had a positive family history of kidney disease." (PMID 36925663, 2023). "Type IV collagen-related nephropathy, in which there is disruption of the normal glomerular basement membrane architecture and kidney disease, has been linked to pathogenic variants in COL4A3, COL4A4, and COL4A59." (PMID 30002862, 2018). "Type IV collagen-related nephropathies are a genetically diverse group of inherited kidney disorders caused by mutations in the collagen type IV alpha-3 (COL4A3), alpha-4 (COL4A4) or alpha-5 (COL4A5) genes, which encode essential components of the glomerular basement membrane (GBM)." (PMID 41562995, 2025).
kidney disease (continued). "Predicted pathogenic variants of the COL4A5 gene were established in one out of 2320 individuals, and COL4A3 and COL4A4 variants in one in 106 individuals in populations without kidney disease." (PMID 36982595, 2023). "In the patient with typical extrarenal features and GBM lamellation (index of family 11), whole exome sequencing using a kidney disorders gene panel identified COL4A4 variant c.2690G>A (p.Gly897Glu), but no additional variants in COL4A3/COL4A4/COL4A5 or other podocyte-related genes." (PMID 36925663, 2023). "Therefore, NGS with a renal disease panel (including exon and reported introns) was performed and CNVs were detected, but only one mutation involving COL4A4 was found without CNVs." (PMID 34858896, 2021). "Given that heterozygous COL4A3/COL4A4 mutations were observed in patients with familial FSGS 2, 4, and FSGS can be secondary to TBMN and AS 36, 37, 38, FSGS may be only a pathological lesion process in the related kidney diseases or secondary to the GBM pathology." (PMID 27469977, 2016).